BMI1 (BMI1 proto-oncogene, polycomb ring finger)
Description:
Component of a Polycomb group (PcG) multiprotein PRC1-like complex, a complex class required to maintain the transcriptionally repressive state of many genes, including Hox genes, throughout development. PcG PRC1 complex acts via chromatin remodeling and modification of histones; it mediates monoubiquitination of histone H2A 'Lys-119', rendering chromatin heritably changed in its expressibility. The complex composed of RNF2, UB2D3 and BMI1 binds nucleosomes, and has activity only with nucleosomal histone H2A. In the PRC1-like complex, regulates the E3 ubiquitin-protein ligase activity of RNF2/RING2.
Synonyms: PCGF4; RNF51; FLVI2/BMI1; flvi-2/bmi-1
Tractability: Small molecule: a structure with a bound ligand is known. PROTAC: UniProt records ubiquitination sites on it; ubiquitination databases record sites on it.
Gene: Protein-coding gene on chromosome 10 (22,321,078 to 22,331,485, forward strand). Ensembl gene ENSG00000168283.
Subcellular location: Nucleus; Cytoplasm
Subcellular location (Human Protein Atlas): Nuclear bodies; Nucleoplasm; Cytosol; Nucleoli
Pathways (Reactome):
Metabolism of proteins: SUMOylation of DNA damage response and repair proteins; SUMOylation of DNA methylation proteins; SUMOylation of RNA binding proteins; SUMOylation of chromatin organization proteins; SUMOylation of transcription cofactors
Gene expression (Transcription): RUNX1 interacts with co-factors whose precise effect on RUNX1 targets is not known; Transcriptional Regulation by E2F6
Cellular responses to stimuli: Oxidative Stress Induced Senescence
Developmental Biology: Differentiation of naive CD4+ T cells to T helper 2 cells (Th2 cells)
Signal Transduction: Regulation of PTEN gene transcription
Gene Ontology:
Molecular function: promoter-specific chromatin binding; protein binding; RING-like zinc finger domain binding; zinc ion binding; chromatin binding; ubiquitin-protein transferase activator activity
Biological process: chromatin remodeling; hemopoiesis; negative regulation of gene expression, epigenetic; negative regulation of transcription by RNA polymerase II; positive regulation of fibroblast proliferation; positive regulation of ubiquitin-protein transferase activity; regulation of gene expression; heterochromatin formation; negative regulation of DNA-templated transcription; segment specification; positive regulation of B cell proliferation; positive regulation of immature T cell proliferation in thymus
Cellular component: cytoplasm; nucleus; PcG protein complex; PRC1 complex; ubiquitin ligase complex; chromatin; nucleoplasm; heterochromatin; nuclear body
Genetic constraint (gnomAD): Loss-of-function variants: 9 observed, 38.06 expected, observed/expected ratio (o/e) 0.24, 90% interval 0.14 to 0.41. The upper end of that interval is the gene's LOEUF score, 0.41, which puts it in group 1 of 6, group 1 being the genes least tolerant of losing a copy. Missense variants: 252 observed, 408.83 expected, observed/expected ratio (o/e) 0.62, 90% interval 0.56 to 0.68. Synonymous variants: 131 observed, 133.99 expected, observed/expected ratio (o/e) 0.98, 90% interval 0.85 to 1.13.
Homologues: Orthologues: chimpanzee BMI1 (100% identical), macaque COMMD3 (100% identical), guinea pig BMI1 (99% identical), pig BMI1 (99% identical), dog BMI1 (99% identical), mouse Bmi1 (97% identical), rat Bmi1 (95% identical), tropical clawed frog bmi1 (89% identical), zebrafish bmi1a (79% identical), zebrafish bmi1b (76% identical), Drosophila melanogaster Su(z)2 (37% identical), Drosophila melanogaster Psc (18% identical). Paralogues in human: PCGF2 (65% identical), PCGF1 (27% identical), PCGF6 (25% identical), PCGF3 (25% identical), PCGF5 (25% identical), RING1 (19% identical), RNF2 (18% identical).
Diseases named in the same sentence as BMI1 in open-access papers:
BMI1 is named in the same sentence as 308 diseases in open-access papers, as found by Europe PMC text mining. Sharing a sentence is not in itself a finding about the gene and the disease. The quoted sentences say what the papers report.
breast carcinoma (177 papers, 2007 to 2026). "Moderate Bmi-1 expression is necessary for development, whereas abnormally high Bmi-1 expression has been linked with the oncogenesis, development and prognosis of various tumor types, including glioma, colorectal cancer, breast cancer and prostate cancer." (PMID 37219449, 2023). "In a recent study, the authors explored hTERT mRNA expression levels in breast cancer samples with a panel of 30 known stem cell marker molecules; in this panel, there was a significant association between hTERT and BMI1 expression in cancerous tissue." (PMID 34442383, 2021). "Bmi1 is upregulated in tumor cells and tissue and associated with poor prognosis in various human cancers including breast cancer, lymphomas, melanoma, colon cancer, ovarian cancer, hepatocellular carcinoma, NPC, lung cancer, and neuroblastoma." (PMID 33014838, 2020). "Univariate survival analysis showed that high BMI1 protein expression was significantly associated with longer survival in terms of breast cancer-specific survival (BCSS) in the whole BC cohort (P = 0.02)." (PMID 32524353, 2020). "Bmi1 expression was also associated with favorable overall survival in a sample of 960 breast cancer patients, and high Klf4 expression was reported to be associated with longer disease-free survival and overall survival of breast cancer patients." (PMID 28422735, 2017). "In patients with uterine cervical or breast cancers it has been shown that high BMI1 mRNA expression in plasma is associated with poor survival." (PMID 28445986, 2017). "By contrast, the results of two large studies of breast cancer patients demonstrated that high BMI1 protein expression in the primary tumor is associated with a favorable prognosis, and similar results were obtained in glioblastoma patients." (PMID 28445986, 2017). "Overexpression of BMI1 has been identified in various cancer tissues and in breast cancer it is associated with poor prognosis, contributing to cell proliferation, invasion, and metastasis." (PMID 28655885, 2017). "Immunohistochemistry revealed an inverse association of ERα and Bmi1 expression in human breast cancer tissue." (PMID 26023734, 2015). "BMI1 expression has been associated with tumor invasion and metastasis in lung and breast carcinoma." (PMID 24708840, 2014). "Further, reduced Bmi1 rendered breast cancer cells increasingly susceptible to chemotherapeutic drug doxorubicin and abrogated tumor formation in nude mice." (PMID 25348805, 2014). "Bmi1 expression in breast cancer has also been found to be associated with other tumor genes and in vitro models have demonstrated Bmi1 is required for metastasis of breast cancer." (PMID 24559156, 2014). "Despite the fact our investigation revealed that Bmi1 expression is determined by ERα status in breast cancer, it must be noted that nearly half of the cases with loss of ERα still expressed Bmi1 or cyclin D1 which is another ERα target gene." (PMID 24559156, 2014). "Since PRC1 exhibits a variable composition of proteins we also investigated Bmi1, that has been found overexpressed in breast cancer, where it is associated with a good prognosis." (PMID 24742605, 2014). "Significantly, elevated Bmi1 expression has been associated with poor prognosis in several cancers including breast carcinomas, highlighting the prognostic relevance of Bmi1 expression." (PMID 25348805, 2014). "Much evidence have linked BMI1 to aggressive, malignant behavior, and poor clinical outcome in various cancer cells, including prostate cancer, breast cancer, lung cancer, ovarian cancer, and hepatocellular cancer." (PMID 23820733, 2013). "A critical feature of GLI1 in this context is its ability to induce BMI-1, a transcriptional repressor that has been implicated in the function of mammary tumour stem cells." (PMID 23436775, 2013). "Distant metastases have been reported to be associated with Bmi-1 expression in breast cancer, melanoma, gastric cancer, and colon cancer." (PMID 20936121, 2011).
breast carcinoma (continued). "Bmi-1 protein is detected in only 25% of African breast cancer patients and is associated with a low histological grade." (PMID 21276221, 2011). "High Bmi-1 expression predicts an unfavorable patient prognosis and serves as a high risk indicator in breast cancer." (PMID 21276221, 2011). "Univariate Cox regression analyses revealed that a high level of Bmi-1 was associated with a significantly increased risk of death in breast cancer patients (***P = 0.001)." (PMID 21276221, 2011). "Two recent reports also documented the association of BMI1 expression with survival after breast cancer." (PMID 19099573, 2008). "When we correlated gene expression with clinical-pathological features of the tumors, some analyzed parameters in primary breast cancer samples showed significant associations with Bmi-1 mRNA expression levels in plasma." (PMID 17711569, 2007). "BMI1 is implicated in the induction of apoptosis in breast cancer cells by miR-15a/miR-16." (PMID 38807590, 2024). "It has been demonstrated that Bmi-1 overexpression might considerably associate with a worse OS in breast cancer cases." (PMID 33639931, 2021). "To test this hypothesis, we genotyped 4 variants in ATM gene and 2 variants in BMI‐1 gene in 524 breast cancer cases and 518 cancer‐free controls from Heilongjiang province, China to see whether they can alter the risk of breast cancer." (PMID 29691986, 2018). "Similarly to PRC2, BMI1 was also associated with good prognosis in breast cancer and poor prognosis in colorectal cancer." (PMID 29415665, 2018). "We tested the hypothesis that genetic variation in ATM and BMI‐1 genes can alter the risk of breast cancer through genotyping 6 variants among 524 breast cancer cases and 518 cancer‐free controls of Han nationality." (PMID 29691986, 2018). "Consistent with our results, research on ovarian cancer, breast cancer, clear cell renal cancer, laryngeal carcinoma, cervical cancer, and esophageal adenocarcinoma have reported an association between high Bmi-1 expression and an unfavorable prognosis." (PMID 28122538, 2017). "As an oncogene and stem cell marker, Bmi-1 can maintain the self-renewal of CSCs in some tumors, including breast cancer and glioma, but whether Bmi-1 is implicated in the regulation of gastric CSCs is still unclear." (PMID 27644439, 2016). "Furthermore, immunohistochemistry staining for Bmi1, ERα and E-cadherin revealed that Bmi1 expression was inversely associated with ERα and E-cadherin levels in human breast cancer specimens in a significant manner (P < 0.05)." (PMID 26023734, 2015). "Few studies have associated Bmi1 with radio-resistance and drug-resistance in breast cancer cells." (PMID 25348805, 2014). "Increased Bmi1 expression has been associated with increased aggression in other cancer types and correlates with tumor invasion and metastasis in breast cancer." (PMID 23437065, 2013). "Furthermore, a high level of Bmi-1 indicates an unfavorable overall survival and serves as a high risk marker for breast cancer." (PMID 21276221, 2011). "In our current study, we demonstrated that Bmi-1 induced invasion, which might be associated with activation of the Akt pathway in breast cancer cells." (PMID 21276221, 2011). "The current study first illustrated the expression of Bmi-1 in primary breast cancer tissues, followed by demonstrating the association between the Bmi-1 expression and clinicopathologic parameters and finally addressed the role of Bmi-1 in breast cancer prognosis in a large series of 252 samples." (PMID 21276221, 2011). "An 11-gene signature, based on a mouse model of metastatic prostate cancer and on BMI1-deficient versus BMI1-proficient neurospheres, has been suggested to reflect BMI1-regulated 'stem cell-ness' pathways and to predict a poor outcome in breast cancer." (PMID 19099573, 2008). "However, more recent reports suggest that BMI1 overexpression is associated with a good outcome in breast cancer." (PMID 19099573, 2008).
breast carcinoma (continued). "Additionally, BMI1 has been implicated in promoting breast cancer and endometrial cancer." (PMID 38511143, 2024). "The expression of ERα usually increases both levels of Bmi1 and cyclin D1, while loss of ERα-coupled Bmi1 activity may result in aberrant p16INK4a expression and is also generally consistent with a more aggressive breast cancer phenotype." (PMID 24559156, 2014). "Assessment of Bmi-1 expression might help to identify a high-risk subgroup of breast cancers." (PMID 21276221, 2011). "Experimental studies convincingly link BMI-1 to carcinogenesis, for instance, aberrant expression of BMI-1 has been associated with malignant tumors of the hematopoietic and lymphatic systems, melanoma, neuroblastoma, endometrial carcinoma, non-small cell lung cancer and breast cancer." (PMID 21311599, 2011). "In this study, six CSC markers (CD44hi/CD24lo, CD24, Ep-CAM, ALDH1, CD10, and BMI1) were assessed in a surgical cohort of 73 breast cancer patients." (PMID 40943144, 2025). "For instance, our previous investigation suggested LINC00960 to promote breast cancer via the hsa-miR-34a-5p, hsa-miR-16-5p, BMI1, KRAS, and AKT3 network." (PMID 39995981, 2025). "miR-200c modulated the expression of BMI1 Proto-Oncogene, Polycomb Ring Finger (BMI1), a regulator of stem cell self-renewal, and inhibited the clonal expansion of breast cancer cells." (PMID 38360723, 2024). "In breast cancer, Gli-1 and Gli-2 overexpression induced Bmi-1 expression, which was necessary to promote self-renewal of both normal and malignant mammary stem cells." (PMID 36726797, 2023). "Bmi-1 is considered to be oncogenic, as it contributes to the progression of various cancers and is upregulated in glioma, colorectal cancer, breast cancer and prostate cancer." (PMID 37219449, 2023). "We performed hierarchical clustering of ROR1 with 24 EMT-related genes including the Hippo signaling pathway genes from the MSigDB database along with WNT5a, BMI1, BCL2, and GLI1 prompted by associations noted in prior studies on breast cancer or CLL." (PMID 37029329, 2023). "We described for the first time that the spatial nuclear location of BMI1 protein triggers RS response in breast cancers." (PMID 35110528, 2022). "The breast cancer CSCs have the BMI1 protein placed around stalled replication forks to engage RAD51 to activate the homologous recombination machinery to confirm that the BMI1/RAD51 axis is necessary to prevent cisplatin-induced cisplatin DNA damage." (PMID 36550571, 2022). "The inhibition of BMI1 can elevate the sensitivity of tumor cells to chemoradiotherapy for tongue and breast cancer." (PMID 36139536, 2022). "Our previously published data also show that compared to adherent breast cancer cells, suspension cultures promote stemness, as shown with real-time quantitative PCR (qRT-PCR) for BMI1, NANOG and CD44." (PMID 35195687, 2022). "On the other hand, ectopic expression of miR-128 in BCSCs suppresses breast cancer progression and induces apoptosis by downregulating BMI-1 and ABCC5 expression." (PMID 33413418, 2021). "A recent study of breast cancer reported that inhibition of BMI1 expression can eliminate BMI1-positive cancer stem cells, triggering endogenous immune responses, including CD8+ T cell expansion, in tumor cells." (PMID 34442383, 2021). "Currently, knockdown of miR-128 in breast tumor-initiating cells was reported to induce chemotherapeutic resistance, which contributes to chemotherapeutic resistance in breast cancers by targeting of Bmi-1 and ATP binding cassette subfamily C member 5 (ABCC5)." (PMID 33472642, 2021). "Other studies reveal BMI1 also adds a tumorigenic capacity in colon cancer, medulloblastoma, laryngeal cancer, breast cancer, prostate cancer, and pancreatic cancer." (PMID 33804165, 2021). "It modulates the transition of G1 to S phase by regulating the expression of protein Bmi-1 in breast cancer." (PMID 34575183, 2021).
breast carcinoma (continued). "Using the Genomics of Drug Sensitivity in Cancer (GDSC) and the Catalog of Somatic Mutations in Cancer (COSMIC) databases, we performed high-throughput drug sensitivity screening in breast cancer cell lines according to BMI1 expression." (PMID 34442383, 2021). "BMI1 overexpression increased breast cancer sphere formation and promoted EMT, with increased expression of stemness-related genes through activation of Nanog expression via the NF-κB pathway." (PMID 34360879, 2021). "It was demonstrated that the BMI1 upregulation in 5-fluoro uracil-resistant breast cancer cell lines, such as MDA-MB-231 (mesenchymal stem-like TNBC) and MDA-MB-453 (TNBC)." (PMID 34360879, 2021). "BMI1 has been found to be a characteristic marker of poor prognosis in patients with breast cancer, nasopharyngeal carcinoma, oesophageal squamous cell carcinoma and gastric carcinoma." (PMID 34321511, 2021). "It was previously reported that B cell‐specific Moloney mouse leukemia virus integration site 1 (Bmi1) activates the Wnt pathway by inhibiting the expression of DKK1 in breast cancer cell lines and 293T cells." (PMID 33639034, 2021). "The aim of this study was to evaluate BMI1 expression and to analyze clinicopathological parameters and survival according to BMI1 expression in our cohort of patients with breast cancer." (PMID 34442383, 2021). "A previous study revealed high BMI1 expression in high-grade breast cancer tissues compared to normal breast tissues." (PMID 34442383, 2021). "Activation of the Shh pathway leads to increased BMI1 expression in medulloblastoma and breast cancer." (PMID 33499351, 2021). "We identified telomerase inhibitor IX, a drug with potent activity against breast cancer cell lines with high BMI1 expression." (PMID 34442383, 2021). "B-lymphoma Moloney murine leukemia virus insertion region-1 (BMI1), a self-renewal gene, has been suggested to be overexpressed in various human cancers, such as ovarian cancer, colorectal cancer, lung cancer, and breast cancer." (PMID 32099526, 2020). "One study showed significant correlation between PD-L1 expression and CSC markers Oct4A, Nanog and BMI1 in a large breast cancer data set." (PMID 33372595, 2020). "For example, BMI1 promoted invasion and metastasis, and high BMI1 expression was correlated with an advanced stage of breast cancer." (PMID 32099526, 2020). "The role of BMI-1 in EMT demonstrated in previous studies with breast cancer cells further support our findings." (PMID 32348447, 2020). "Bmi1 increases the level of p-Akt and enhances tumour cell proliferation, migration, and anti-apoptotic abilities in the human breast carcinoma cell line MCF-753." (PMID 30679589, 2019). "qRT‐PCR results revealed that Jagged1, ZEB1 and Bmi1 mRNAs were up‐regulated in breast cancer tissues compared with matched adjacent tissues." (PMID 31599500, 2019). "For instance, in breast cancer, the knockdown of BMI-1 expression impaired the tumor initiation ability of CSCs, while the rescue of BMI-1 expression restored tumor formation." (PMID 31382410, 2019). "BMI-1 is expressed in a number of malignancies, such as prostate, lung, ovarian, pancreatic, lymphoma, glioma, acute myeloid leukemia and breast cancer, among others." (PMID 31382410, 2019). "Bmi1 inhibition has been shown to enhance the sensitivity of breast cancer cells to 5-FU and radiation." (PMID 30918246, 2019). "PTC-209 at a concentration of 2.5-μM decrease Bmi-1 protein expression by about 30% as reported in FMMC 419II mouse mammary tumor cells." (PMID 31695609, 2019). "A recent study has demonstrated that the activity of the estrogen receptor α (ERα)-coupled BMI1 signature impacts p16INK4a and cyclin D1 status and correlates with the tumor molecular subtype and biologic behavior in breast cancer." (PMID 29685168, 2018). "Expression of BMI1 in breast cancer stem cells is mediated by HSP90α through nuclear translocation of c-Myc and EZH2." (PMID 30018256, 2018).